INS (insulin)
Diseases named in the same sentence as INS in open-access papers (continued):
Sharing a sentence is not in itself a finding about the gene and the disease.
liver disease (213 papers, 2008 to 2026). "Reduced muscle mass and strength increase the risk of liver disease progression, given the chronic inflammation, decreased insulin sensitivity, and mitochondrial dysfunction." (PMID 41226003, 2025). "Given the emerging interest in ZAG’s involvement in metabolic diseases such as metabolic-dysfunction-associated steatotic liver disease, this study aimed to investigate the acute effects of insulin on ZAG levels both in vivo and in vitro." (PMID 40564902, 2025). "The restoration of hepatic Mc3r resulted in improvements in adiposity, metabolic dysfunction-associated steatotic liver disease, and insulin sensitivity." (PMID 39956805, 2025). "There was also an association between the age of insulin introduction and the presence of CF liver disease." (PMID 40430241, 2025). "This study elucidates how α-LA influences on the sphingolipid and insulin transduction pathways in the development of metabolic-associated steatotic liver disease induced by high-fat feeding." (PMID 38794739, 2024). "Among these, dietary habits, in conjunction with exercise, play an important factor in achieving sustainable weight loss, which is linked to significant improvements in insulin resistance and metabolic parameters associated with steatotic liver disease." (PMID 39796579, 2024). "Its pathophysiology is complex and includes a loss of pancreatic islet cells, which causes insulin and glucagon deficiency, fluctuating insulin resistance, intestinal abnormalities, and liver disease." (PMID 31878961, 2019). "Recent preclinical data have shown that supplementation with omentin-1 may inhibit the NF-κB and MAPK signaling pathways to maintain glucose and insulin metabolism in the context of metabolic dysfunction-associated steatotic liver disease." (PMID 40241486, 2025). "In our previous laboratory investigations, we have observed that the combination therapy of NAC and insulin exhibits superior efficacy in managing various complications associated with T1DM, including cardiomyopathy, hepatic disorders, and renal dysfunction when compared to insulin monotherapy." (PMID 40001479, 2025). "Furthermore, butyric acid can prevent the progression of metabolic dysfunction-associated steatotic liver disease by suppressing insulin-mediated fat accumulation and increasing anti-inflammatory effects via regulatory T cells." (PMID 38398848, 2024). "One explanation for the hepatoprotective association between Omega-3 intake and liver disease may be that Omega-3 fatty acids improve insulin sensitivity, which is strongly associated with protection against NAFLD." (PMID 37538264, 2023). "Portal hypertension is associated with malnutrition, the mechanisms of which include impaired digestion and absorption due to impaired intestinal peristalsis and edema, and insulin resistance." (PMID 38024081, 2023). "These mice are severely obese and insulin resistant, two conditions that could cause myosteatosis independently from liver disease severity." (PMID 33244884, 2021). "This period of childhood development is associated with changes in body fat deposition, insulin sensitivity, and hepatic antioxidant defenses, which may confer greater susceptibility to alterations in lipid metabolism and liver disease." (PMID 23781345, 2013). "Previous work has demonstrated that the gene, Arrdc3,modulates insulin action and glucose metabolism in the liver, which may be important for metabolic disorders, including metabolic dysfunction-associated steatotic liver disease." (PMID 41007411, 2025). "Therefore, it might provide the rational basis for a personalized management of patients with NAFLD taking into account nutritional habits and insulin sensitivity state that may pose an increased risk of liver disease onset and progression." (PMID 37507858, 2023).
liver disease (continued). "PUFAs promote fatty acid oxidation and inhibit lipogenesis, decrease inflammation and improve insulin sensitivity, which are critical factors in the prevention and management of various liver diseases." (PMID 40292496, 2025). "Plant metabolites, especially the polyphenols, have been well characterized as drug treatments in alleviating liver diseases: oxidative stress, metabolism of lipids, resistance to insulin, and inflammatory." (PMID 40892759, 2025). "Metformin, however, has been reported to improve lipid profiles and insulin metabolism, reduce body weight, and decrease biochemical markers of liver disease in patients with NAFLD." (PMID 41009577, 2025). "It is well known that aldosterone and cortisol excess promote steatotic liver disease through different mechanisms: impaired insulin action, increased lipolysis and gluconeogenesis." (PMID 40079488, 2025). "In individuals with T2DM and liver disease classified as Child-Pugh Class B or C, the use of non-insulin antihyperglycemic medications should be approached with caution or altogether avoided." (PMID 38559691, 2024). "In patients with advanced liver disease, the selection of non-insulin antihyperglycemic drugs is complex." (PMID 38559691, 2024). "IGF1-induced insulin sensitization has been in rodent models of liver disease, including models of NAFLD and NASH, and has been demonstrated to have antifibrotic properties." (PMID 38469144, 2024). "For example, adherence to a KETO for 6 days in patients with steatotic liver disease decreased intrahepatic triglycerides by 31% and hepatic insulin resistance by 58% as measured via isotopomer nuclear magnetic resonance tracing." (PMID 39796579, 2024). "Improved insulin sensitivity helps in better glucose regulation, reducing the metabolic burden on the liver and preventing the exacerbation of liver diseases." (PMID 39125411, 2024). "Silymarin is found to be able to intervene in multiple therapeutic targets of liver diseases, the fat accumulation process in liver, hepatocyte mitochondria function and even insulin resistance are modulated with silymarin treatment." (PMID 37719856, 2023). "Increased intake of whole grains and their component bran has been reported to have beneficial effects on diseases related to liver disease and liver cancer, including glycemia, insulin sensitivity, metabolic regulation, and reduced inflammation, etc." (PMID 37349735, 2023). "Important liver diseases that result from glycogen accumulation include genetic glycogen storage diseases and acquired diseases resulting from insulin dysregulation and/or medication effects." (PMID 37047105, 2023). "Studies have shown that weight loss can improve insulin sensitivity and reduce liver fat, which can ultimately prevent NAFLD or improve existing liver diseases." (PMID 37992029, 2023). "They excluded subjects with renal and liver disorders, those on hormonal therapy, those with a history of recent surgery, pregnant and lactating women and those who are undergoing insulin preparation therapy." (PMID 37049495, 2023). "The ability for insulin inactivation in the liver is impeded in the process of liver disease, and as a result insulin levels in the blood are dramatically elevated, ultimately leading to lower glucose levels." (PMID 35215494, 2022). "Adiponectin, one of the well-known adipokines, has insulin-sensitization and anti-inflammatory effects in insulin target tissues including liver, and acts as an important regulator for the development of hepatic diseases." (PMID 36052075, 2022). "Of these, miR-34a-5p, miR-122-5p, miR-27b-3p and miR-885-5p have been identified to play a role in fat and/or lipid metabolism, insulin sensitivity or liver disease." (PMID 35194110, 2022). "For example, a recent study shows that disruption of the clock gene BMAL1 impacts insulin sensitivity and liver disease." (PMID 36321857, 2022).
liver disease (continued). "Liver diseases are characterized by depletion of hepatic glycogen, changes in insulin synthesis, and reduced signaling in the liver." (PMID 34076201, 2021). "Fructose is among the main drivers of liver disease, because it feeds into hepatic de novo lipogenesis, thus increasing the amount of steatosis and consequent lipotoxicity, and moreover promoting insulin resistance in the context of a hypercaloric diet." (PMID 34201382, 2021). "Children with cerebral edema or known chronic kidney/liver disease or who had received pre-referral fluids and/or insulin were excluded." (PMID 31898531, 2020). "SHBG concentration is strongly influenced by various factors, such as sex steroid balance, drugs, thyroid hormone, insulin, dietary composition, and liver diseases." (PMID 30881692, 2019). "Natural polyphenol is a plant-based secondary metabolite with a pharmacological effect on oxidative stress, lipid metabolism, insulin resistance, and inflammation, and encompasses the most crucial pathological process in the etiology of liver disease." (PMID 31849423, 2019). "Strikingly, polyphenols have been found to possess a variety of pharmacological effects on oxidative stress, lipid metabolism, insulin resistance, and inflammation, which are the most important pathological processes in the etiology of liver diseases." (PMID 29507653, 2018). "In dairy cows, numerous inflammatory diseases (metritis, mastitis, orthopedic diseases, subacute ruminal acidosis) can affect insulin sensitivity and potentially promote lipolysis, ketogenesis and hepatic diseases." (PMID 28107442, 2017). "Patients provided fasting blood samples and we examined the correlation of liver fat with indices of insulin resistance, lipolysis and metabolic liver disease using Kendall Tau statistics." (PMID 27399690, 2016). "For example, the induction of TNF-α causes phosphorylation of IRS-1 at Ser312 and impedes insulin signaling, especially in HCV patients with more severe liver disorders." (PMID 25645159, 2015). "Conversely, IL-10 production has beneficial effects on insulin sensitivity and protects against liver disease." (PMID 26588700, 2015). "Oxidative stress is a major factor in the development of various liver diseases, affects liver function and induces hepatic insulin resistance, and is ultimately attributed to liver injury." (PMID 25045414, 2014). "However, insulin may be considered as the first-line treatment in in lean subjects or people with severe weight loss, acute illness or systemic underlying diseases such as renal or hepatic diseases." (PMID 24593991, 2014). "Muscle mitochondrial dysfunction does not appear to be a major driving force contributing to muscle fat accumulation, insulin resistance or liver disease." (PMID 22359625, 2012). "Furthermore, our study comprehensively addressed multiple pathological features of NASH beyond impaired insulin signaling, such as inflammation and metabolic dysregulation, offering a broader understanding of GP’s therapeutic potential in liver disease." (PMID 40869401, 2025). "We did not look specifically at particular oral or other anti‐glycaemic agents; however, sulphonyureas and insulin are used most typically for diabetic control (> 90%), due to the tendency to primarily use these agents in patients with advanced or decompensated liver disease." (PMID 40664615, 2025). "There is also a presumption that the activity of pancreatic beta cells in insulin secretion could be altered by various factors (e.g., environment, genetics, and the etiology of the liver disease)." (PMID 40491591, 2025). "Reduced insulin sensitivity and impaired insulin secretion have been reported in CFLD patients with portal hypertension, and these factors may contribute to the increased risk." (PMID 40430241, 2025). "Therefore, the decrease in skeletal muscle mass can result in reduced insulin sensitivity, a key factor in the development of steatotic liver disease." (PMID 38616253, 2024).
liver disease (continued). "Published data on the effects of SB on the serum levels of ALT, AST, GGT, ALP, bilirubin, albumin, glucose, insulin, cholesterol, triglycerides, biomarkers of systemic inflammation, oxidative stress, and bacterial translocation in various liver disorders were systematized." (PMID 39203520, 2024). "Our biochemical analyses prove that C. spinosa compounds may exert regulatory influence over critical biological processes involved in these liver disorders, including inflammation, oxidative stress, lipid metabolism, and insulin sensitivity." (PMID 39055878, 2024). "GW extract also prevented liver disease, reduced blood lipids, and regulated insulin." (PMID 37432154, 2023). "Furthermore, BDNF can also modulate insulin signaling and liver disease in animal models of cirrhosis and alcohol-induced liver disease." (PMID 37377968, 2023). "The anti-inflammatory, insulin-sensitizing, and lipid-metabolizing effects of Omega-3 fatty acids may contribute to their potential benefits in the prevention of liver diseases, although the exact mechanisms are not fully understood." (PMID 37538264, 2023). "Thus, early detection and treatment of aberrant insulin signaling are critical for prevention and treatment of liver disease." (PMID 36942499, 2023). "On the contrary, we detected a link between the presence of myosteatosis and reduced dry body weight implying that mechanisms other than insulin resistance or fat accumulation might explain the high rate of myosteatosis in end-stage liver disease." (PMID 37176772, 2023). "Future studies might take a closer analysis of hepatic insulin signaling in the advanced stages of liver disease to determine whether these changes might be occurring, especially since this could impact the life span of the patients." (PMID 36148775, 2022). "There is a bidirectional relationship between the liver and IR: IR and secondary hyperinsulinism lead to liver disease through lipid accumulation, and the liver disease exacerbates IR, transforming impaired glucose tolerance into overt diabetes mellitus through insulin metabolism impairment." (PMID 35683431, 2022). "In conclusion, insulin use should be avoided as long as possible in advanced liver disease." (PMID 34172646, 2022). "Liver disease and inflammation caused by HBV during pregnancy may lead to reduced insulin sensitivity." (PMID 34801053, 2021). "High insulin levels are therefore the results of multiple drivers, involving both environmental and genetic factors, of which balance determines the phenotype and the natural history of liver disease." (PMID 34201382, 2021). "Monoclonal antibodies targeting Chi3L1 protein function may significantly improve insulin sensitivity and decrease lipid accumulation and may alter the progression of this serious liver disease." (PMID 33498326, 2021). "However, there is also a different voice, such as another research which was conducted to detect the expression of human IRS-1 and insulin signaling proteins under different pathophysiologic conditions of hepatic disease." (PMID 32695243, 2020). "Liver clearance of insulin is further reduced with the advancement of disease (i.e., the transition from compensated to decompensated liver cirrhosis as designated by Child–Pugh classification), due to portal-hypertension-related portosystemic shunting." (PMID 32092909, 2020). "The effects on liver weight correlated with an improvement of liver histology in those animals treated with Insulin-Apo while administration with insulin made the liver disease worse, as shown by hematoxylin and eosin staining and by the lipid-specific staining Oil Red O." (PMID 33679386, 2020). "Thus, the conclusion that the relationships among insulin resistance and metabolic alteration across different liver diseases needs further study." (PMID 31223344, 2019).
liver disease (continued). "Liver diseases such as non‐alcoholic fatty liver disease (NAFLD) and non‐alcoholic steatohepatitis (NASH) are characterized by excess hepatic accumulation of lipid droplets and triglycerides which are associated with defective insulin action." (PMID 31250564, 2019). "While meta‐regression identified insulin as a comparator explaining 55% of between‐study variance, the residual heterogeneity likely reflects unmeasured confounding from differences in follow‐up duration, baseline liver disease severity, geographic variation, and healthcare systems." (PMID 41388641, 2025). "Insulin may increase adrenergic activity, potentially worsening portal hypertension and edema." (PMID 40429923, 2025). "In addition to their role in fat and/or lipid metabolism, insulin sensitivity or liver disease, some of the identified miRNAs, in particular miR-34a-5p and miR-122-5p, have also been shown to be upregulated in acute ischemic stroke and acute myocardial infarction." (PMID 35194110, 2022). "Patients requiring insulin by age 15 had higher TDI and were more likely to have CF liver disease (p = 0.027, p = 0.037, respectively)." (PMID 40430241, 2025). "In the case of liver disease, the top 10 factors were TYG, AIP, TG, insulin, TYG_BMI, gamma‐glutamyl transferase (GGT), LDL‐c, alanine aminotransferase (ALT), aspartate aminotransferase (AST), and age." (PMID 40874812, 2025). "It is also well‐believed that IR is a key factor in the pathophysiology of liver disease, and lipid markers such as the TG/HDL‐C ratio and TyG index are useful tools for evaluating metabolic dysregulations like insulin levels and IR in women with PCOS." (PMID 38769719, 2024). "In addition to being associated with disturbances in insulin-glucose homeostasis, visceral obesity has been related to alterations in plasma lipoprotein-lipid levels, particularly increased plasma triglyceride and low HDL concentrations, as well as with liver disease." (PMID 38066623, 2023). "The potential benefit of exercise on liver disease was first studied in NAFLD, of which the key pathophysiological mechanism is insulin resistance." (PMID 32159517, 2020). "A number of studies have demonstrated a reduced risk of liver disease in patients with NAFLD who consume low or moderate amounts of alcohol, and it has been suggested that these levels of alcohol use may be associated with beneficial effects of insulin sensitivity in post-menopausal women." (PMID 28659136, 2017). "Our studies confirmed a potential link between palmitate, insulin signaling and DSP, and are currently further investigating the mechanisms contributing towards progression to more severe forms of liver disease." (PMID 22132232, 2011). "Severity of liver disease had no impact on the mean difference in insulin requirements pre‐ and 6 months post‐transplant, in any of the scoring systems used." (PMID 40664615, 2025). "In this study, we investigated whether ursodeoxycholic acid (UDCA), a widely used bile acid sequestrant used therapeutically in liver diseases, induces GLP-1 secretion, and assessed its effects on glucose and insulin levels in healthy subjects." (PMID 23450079, 2013). "In conclusion, by influencing insulin signaling, fibrogenesis, HSC activation, EMT and cellular plasticity, TGF-β signaling emerges as a pivotal mediator in liver pathogenesis, providing insights into the intricate interplay between metabolic dysregulation and the progression of liver disease." (PMID 40260391, 2025). "Also, SGLT-2 inhibitors may improve insulin sensitivity and reduce hepatic fat in T2DM patients, delaying liver disease development." (PMID 39407960, 2024). "While the focus of the study was on redox regulation and insulin sensitivity responses in adult men and women with T2DM, the unique amino-acid profile suggests that other conditions such as liver disease and cardiovascular disease may benefit from KDP supplementation." (PMID 37812879, 2023).